FBXO3 (F-box protein 3)
Description:
Substrate recognition component of the SCF (SKP1-CUL1-F-box protein)-type E3 ubiquitin ligase complex, SCF(FBXO3), which mediates the ubiquitination and subsequent proteasomal degradation of target proteins. Mediates the ubiquitination of HIPK2 and probably that of EP300, leading to rapid degradation by the proteasome. In the presence of PML, HIPK2 ubiquitination still occurs, but degradation is prevented. The SCF(FBXO3) also acts as a regulator of inflammation by mediating ubiquitination and degradation of FBXL2 in response to lipopolysaccharide (LPS). The SCF(FBXO3) complex specifically recognizes FBXL2 phosphorylated at 'Thr-404' and promotes its ubiquitination. (Microbial infection) Associates with the Rift valley fever virus NSs to form a remodeled E3 ligase that triggers efficient proteasomal degradation of targeted proteins. The filamentous E3 ligase targets the TFIIH complex leading to robust inhibition of antiviral immunity and enhances viral pathogenesis.
Synonyms: FBX3; FBA
Tractability: PROTAC: ubiquitination databases record sites on it; its protein half-life has been measured.
Gene: Protein-coding gene on chromosome 11 (33,740,939 to 33,774,543, reverse strand). Ensembl gene ENSG00000110429.
Subcellular location: Nucleus
Subcellular location (Human Protein Atlas): Nucleoplasm; Cytosol
Gene Ontology:
Molecular function: protein binding; ubiquitin-like ligase-substrate adaptor activity; ubiquitin-protein transferase activity
Biological process: response to lipopolysaccharide; SCF-dependent proteasomal ubiquitin-dependent protein catabolic process; proteolysis; regulation of inflammatory response; protein ubiquitination
Cellular component: nucleus; SCF ubiquitin ligase complex; cytoplasm
Genetic constraint (gnomAD): Loss-of-function variants: 12 observed, 43.21 expected, observed/expected ratio (o/e) 0.28, 90% interval 0.18 to 0.45. The upper end of that interval is the gene's LOEUF score, 0.45, which puts it in group 1 of 6, group 1 being the genes least tolerant of losing a copy. Missense variants: 330 observed, 490.3 expected, observed/expected ratio (o/e) 0.67, 90% interval 0.61 to 0.74. Synonymous variants: 151 observed, 174.1 expected, observed/expected ratio (o/e) 0.87, 90% interval 0.76 to 0.99.
Homologues: Orthologues: chimpanzee FBXO3 (100% identical), macaque FBXO3 (99% identical), pig FBXO3 (99% identical), rat Fbxo3 (96% identical), mouse Fbxo3 (95% identical), dog FBXO3 (88% identical), guinea pig FBXO3 (86% identical), zebrafish fbxo3 (65% identical), tropical clawed frog fbxo3 (65% identical). Paralogues in human: POLDIP2 (17% identical).
Diseases named in the same sentence as FBXO3 in open-access papers:
FBXO3 is named in the same sentence as 27 diseases in open-access papers, as found by Europe PMC text mining. Sharing a sentence is not in itself a finding about the gene and the disease. The quoted sentences say what the papers report.
breast carcinoma (5 papers, 2019 to 2025). "To investigate the causative role of FBXO3 in p110αH1047R-induced breast cancer cell migration and tumor metastasis, we performed rescue experiments." (PMID 38134227, 2023). "We next investigated the causal role of up-regulated Twist1 in FBXO3-induced breast cancer cell migration and tumor metastasis." (PMID 38134227, 2023). "Our previous study demonstrates that ΔNp63α is a common inhibitory target in oncogene-induced cell motility and tumor metastasis, we therefore investigated whether FBXO3 can regulate cell migration of breast cancer cells and whether it is implicated in ΔNp63α." (PMID 38134227, 2023). "FBXO3 promotes breast cancer metastasis through K48-linked polyubiquitination of the ΔNp63α." (PMID 35127719, 2021). "Clinically, elevated expression of p110α/FBXO3/USP4/Twist1 is associated with poor overall survival (OS) and recurrence-free survival (RFS) of breast cancer patients." (PMID 38134227, 2023). "Knockdown of either FBXO3 or USP4 leads to significant inhibition of PI3K-induced breast cancer metastasis." (PMID 38134227, 2023). "Immunohistochemical analyses of human breast tissue microarray (TMA) showed a significant positive correlation of the expression of FBXO3 and Twist1 in breast cancer samples (p < 0.0001)." (PMID 38134227, 2023). "In the following paragraphs, we describe how FBXO3 contributes to inflammatory disorders and cancers, including leukemia, pituitary adenoma, oral squamous cell carcinoma and breast cancer." (PMID 35127719, 2021). "We further analyzed the clinical relevance of the FBXO3-Twist1 axis in breast cancer." (PMID 38134227, 2023). "Taken together, this study reveals that the FBXO3-USP4-Twist1 axis is pivotal in PI3K-mediated breast tumor metastasis and that FBXO3/USP4 may be potential therapeutic targets for breast cancer treatment." (PMID 38134227, 2023). "Notably, IHC analyses of human breast TMA showed that USP4 was positively correlated with the expression of FBXO3 or Twist1 in breast cancer samples." (PMID 38134227, 2023). "This study reveals a non-canonical function of the E3 ubiquitin ligase FBXO3 in PI3K-induced breast cancer metastasis, showing that FBXO3 binds to and protects USP4 from aspartyl aminopeptidase (DNPEP)-mediated degradation, resulting in Twist1 protein stabilization and increased tumor metastasis." (PMID 38134227, 2023). "Activation of PI3K signaling (including both expression levels of the PI3K catalytic subunit p110α or the up-regulated ERK phosphorylation) was positively correlated with cell migration capacity as well as FBXO3/USP4/Twist1 protein levels in breast cancer cell lines examined." (PMID 38134227, 2023). "A global microRNA expression profile identified that miR-210 is associated with poor clinical outcomes in breast cancer patients and that this molecule could interact with FBXO3 to promote breast cancer cell proliferation and migration." (PMID 32038996, 2019). "In addition, the high expression of FBXO3 indicates poor prognosis in patients with breast cancer." (PMID 35127719, 2021). "Thus, targeting FBXO3/USP4 may represent a new therapeutic strategy for breast cancer treatment." (PMID 38134227, 2023). "Given the critical role of PI3K signaling in breast cancer metastasis, we evaluated the relationship between PI3K signaling and FBXO3." (PMID 38134227, 2023). "FBXO3 can bind to and stabilize USP4, leading to Twist1 protein stabilization and increased breast cancer cell migration and tumor metastasis." (PMID 38134227, 2023). "In this study, we discovered a noncanonical function of FBXO3 in promoting breast cancer metastasis in an E3 ligase activity-independent manner." (PMID 38134227, 2023). "Interestingly, FBXO3 promotes the ubiquitylation and degradation of ΔNp63α to enhance TGF-β signaling and accelerate tumor metastasis, indicating that FBXO3 may be a potential therapeutic target for advanced breast cancer treatment." (PMID 36362432, 2022).
breast carcinoma (continued). "In this study, we show that FBXO3 plays a vital role in PI3K-mediated breast cancer metastasis independent of its E3 ligase activity and ΔNp63α in breast cancer cells and in mouse." (PMID 38134227, 2023).
atherosclerosis (3 papers, 2021 to 2024). A disease characterized by the build-up of fatty material and calcium deposition in the arterial wall resulting in partial or complete occlusion of the arterial lumen. "Intriguingly, individuals carrying a hypo‐functioning FBXO3 variant are less susceptible to atherosclerosis." (PMID 38778460, 2024). "Another F‐box protein of the SCF complex, FBXO3, can also promote atherosclerosis by enhancing inflammation." (PMID 38778460, 2024). "FBXO3 also potentiates vascular inflammation and increases atherosclerosis." (PMID 35127719, 2021). "Moreover, FBXO3 is known to stimulate cytokine secretion by destabilizing FBXL2 through UPS, and exert its pro-inflammatory effect in a variety of disease models including lung I/R injury, pneumonia, sepsis, and atherosclerosis." (PMID 36362432, 2022).
Sepsis (3 papers, 2021 to 2022). Sepsis is defined as life-threatening organ dysfunction caused by a dysregulated host response to infection. "Moreover, FBXO3 was confirmed to regulate inflammation responses in subjects with sepsis, which was also reported to regulate ΔNp63α degradation and promote tumor metastasis in malignancy." (PMID 35197975, 2022). "The researchers also found that subjects with sepsis had more TRAF and FBXO3 proteins and less FBXL2 protein in circulating white blood cells compared with control subjects." (PMID 35127719, 2021). "Moreover, the circulating FBXO3 and TRAF proteins in sepsis patients had positive correlations with cytokine responses." (PMID 35127719, 2021).
Cerebral ischemia (2 papers, 2020 to 2022). Restriction of arterial blood supply to the brain associated with insufficient oxygenation to support the metabolic requirements of the tissue. "For example, miR-142 exerted neuroprotective effects against cerebral ischemia/reperfusion (I/R) injury through down-regulation of FBXO3." (PMID 33628189, 2020).
leukemia (2 papers, 2021 to 2026). A malignant (clonal) hematologic disorder, involving hematopoietic stem cells and characterized by the presence of primitive or atypical myeloid or lymphoid cells in the bone marrow and the blood. "We highlight that the high expression of FBXO3 is frequently observed in rheumatoid arthritis, leukemia, pituitary adenoma, and oral squamous cell carcinoma." (PMID 35127719, 2021). "Conversely, PML-RAR enhances FBXO3-induced degradation of HIPK2 and p300 in a dose-dependent manner to inhibit transcription, which might contribute to the pathogenesis of leukemia." (PMID 35127719, 2021).
asthma (1 paper, 2015). "Others have been associated with diabetes (ZBED3), asthma (EMID2), and cancer (FBXO3, HOOK2, MT2A, EIF3E, RPH3AL, PTRF, MT1M, STK32A)." (PMID 25748564, 2015).
clear cell renal cell carcinoma (1 paper, 2017). "For instance, FBXW10 gene is found to be hypermethylated in clear cell renal cell carcinoma, while FBXO3 influences TGF‐β signaling by targeting SMURF1 for proteasomal degradation." (PMID 28397399, 2017).
colitis (1 paper, 2019). Inflammation of the colon. "This is similar to previously reported results that demonstrated Fbxo3 and TRAF proteins were highly upregulated in a mouse model of dextran sulfate sodium-induced colitis and hepatic and cerebral I/R injury." (PMID 31178737, 2019).
H1N1 influenza (1 paper, 2019). "BC-1215 or Fbxo3 knockdown attenuated Pseudomonas aeruginosa and H1N1 influenza-induced lung injury." (PMID 31178737, 2019). "Administration of BC-1215, an Fbxo3 inhibitor, has been shown to increase survival and improve lung injury in H1N1 influenza-infected mice." (PMID 31178737, 2019).
influenza (1 paper, 2021). An acute viral infection of the respiratory tract, occurring in isolated cases, in epidemics, or in pandemics; it is caused by serologically different strains of viruses (influenzaviruses) designated A, B, and C, has a 3-day incubation period, and usually lasts for 3 to 10 days. "The importance of FBXL2 and FBXO3 was underscored by two other studies, as targeting FBXO3 in rodents with the small inhibitor BC-1215 significantly ameliorated H1N1-influenza induced lung injury and acute lung injury, by increasing FBLX2 protein levels and decreasing TRAF protein levels." (PMID 33808506, 2021).
ischemic stroke (1 paper, 2022). A stroke disorder caused by obstruction of blood flow to the brain, due to thrombotic (local blood clot formation) or embolic (due to a blood clot or other material traveling from another site) event. "Taken together, our data suggest the therapeutic relevance of FBXO3 to ischemic stroke and provide a new perspective on the mechanism of I/R injury." (PMID 36362432, 2022). "Our data suggest the therapeutic relevance of FBXO3 to ischemic stroke and provide a new perspective on the mechanism of I/R injury." (PMID 36362432, 2022). "Despite the specific interaction between FBXO3 and HIPK2 requiring further study, we believe that our data suggest the therapeutic relevance of FBXO3 to ischemic stroke and provide a new perspective on the mechanism of I/R injury." (PMID 36362432, 2022).
Parkinson disease (1 paper, 2021). A progressive degenerative disorder of the central nervous system characterized by loss of dopamine producing neurons in the substantia nigra and the presence of Lewy bodies in the substantia nigra and locus coeruleus. "Therefore, in view of the importance of the F-box domain in the interaction with DAT, we studied the possible association of the transporter with other F-box proteins that have been implicated in Parkinson disease (such as FBXO7 or FBXO18) or in the stability of FBXL2 (such as FBXO3)." (PMID 34709416, 2021).
Stroke (1 paper, 2022). Sudden impairment of blood flow to a part of the brain due to occlusion or rupture of an artery to the brain. "The FBXO3 level was elevated in neurons after stroke, and siRNA-induced FBXO3 knockdown rescued the neurological deficits caused by I/R injury in SD rats, while si-FBXO3 was also demonstrated to revise neuronal survival in vitro." (PMID 36362432, 2022). "Taken together, the present study identifies an increase of FBXO3 expression in neurons and a peak at 24 h of reperfusion after stroke." (PMID 36362432, 2022). "Western blot (WB) results showed that, compared to the Sham group, FBXO3 protein expression was increased after 6 h of reperfusion and peaked at 24 h post-stroke (Sham group vs. MCAO 1 h/R 24 h group, p < 0.01), so these conditions were chosen for subsequent experiments." (PMID 36362432, 2022). "Collectively, these results suggest that FBXO3 aggravates I/R outcomes after stroke." (PMID 36362432, 2022).
tumor (6 papers, 2021 to 2023). "Studies have shown that FBXO3 contributes to tumor progression but also increases tumor cell apoptosis." (PMID 35127719, 2021). "Our recent study demonstrates that TGF-β1 promotes FBXO3-mediated ΔNp63α protein degradation to enhance tumor metastasis." (PMID 34203341, 2021). "Our recent study demonstrates that TGF-β1 promotes FBXO3-mediated degradation of ΔNp63α to facilitate tumor metastasis." (PMID 34203341, 2021). "E3 ligase FBXO3 promotes ubiquitination of PD-1 of T cells, thereby enhancing anti-tumor immunity." (PMID 37053008, 2023). "The FBXO3-ΔNp63α is critical for TGF-β-induced tumor metastasis." (PMID 35127719, 2021). "Importantly, the p110αH1047R-induced tumor metastasis could also be rescued by silencing of FBXO3 in a mouse metastasis model." (PMID 38134227, 2023). "However, the role of FBXO3 in tumor metastasis remains elusive." (PMID 38134227, 2023). "However, the role of FBXO3 in tumor metastasis is largely unclear." (PMID 38134227, 2023). "FBXO3 functions as a USP4 binding partner to protect USP4 from degradation, which in turn leads to stabilization of Twist1, thereby promoting cell migration and tumor metastasis." (PMID 38134227, 2023). "Notably, FBXO3 can affect cell migration in the MDA-MB-231 cells which do not express detectable ΔNp63α expression, indicating that FBXO3 can impact cell migration independent of ΔNp63α, a common inhibitory target in oncogene-induced tumor metastasis." (PMID 38134227, 2023). "In this study, we discovered a noncanonical function of FBXO3 in tumor metastasis." (PMID 38134227, 2023).
cancer (5 papers, 2015 to 2023). A tumor composed of atypical neoplastic, often pleomorphic cells that invade other tissues. "FBXO3 has been demonstrated to participate in the occurrence and progression of a variety of human cancers." (PMID 35127719, 2021). "Our recent study demonstrates that TGF-β1 promotes FBXO3-mediated ΔNp63α protein proteasomal degradation to facilitate cancer metastasis." (PMID 34203341, 2021). "Our recent study indicates that TGF-β1 promotes FBXO3-mediated ΔNp63α protein degradation to facilitate cancer metastasis." (PMID 34203341, 2021). "We also describe the substrates of FBXO3, which contribute to inflammatory disorders and cancers." (PMID 35127719, 2021). "Moreover, we describe the regulatory mechanism of FBXO3 by carcinogens and cancer preventive agents." (PMID 35127719, 2021). "This suggests that targeting FBXO3 might be a novel strategy for cancer treatment." (PMID 35127719, 2021). "Moreover, we discuss the regulation of FBXO3 by both carcinogens and cancer preventive agents." (PMID 35127719, 2021). "Therefore, FBXO3 can be a novel target in the treatment of human diseases including carcinomas." (PMID 35127719, 2021). "However, the relation between miR-142-3p to FBXO3 in human cancer cells is not yet clear and needs further research." (PMID 35127719, 2021).
infection (2 papers, 2014 to 2016). The state of being infected such as from the introduction of a foreign agent such as serum, vaccine, antigenic substance or organism. "Furthermore, NSs was shown to promote p62 degradation during early stages of infection by assembling the SCFFBXO3 through NSs-FBXO3 interaction." (PMID 26837067, 2016). "Infection of shRNAs against eight F-box proteins (FBXL5, FBXW5, FBXO3, FBXO4, FBXO5, FBXO24, FBXO25 and FBXO27) upregulated Snail1 protein levels (at least by 2-fold) compared with parental cells or cells infected with a control shRNA." (PMID 24157836, 2014).
FBXO3 also shares sentences with these, for which no sentence is quoted: acute respiratory distress syndrome (1 paper); chronic myeloid leukemia (1); diabetes (1); Lung Injury (1); Obesity (1); oral squamous cell carcinoma (1); pituitary adenoma (1); pneumonia (1); rheumatoid arthritis (1); Streptococcus pneumonia (1); viral infection (1).